MTND4LP30 (MT-ND4L pseudogene 30)
Gene: Processed pseudogene on chromosome 5 (134,928,030 to 134,928,326, reverse strand). Ensembl gene ENSG00000198868.
Diseases named in the same sentence as MTND4LP30 in open-access papers:
MTND4LP30 is named in the same sentence as 1 disease in open-access papers, as found by Europe PMC text mining. Sharing a sentence is not in itself a finding about the gene and the disease. The quoted sentences say what the papers report.
calcification (1 paper, 2025). Process by which organic tissue becomes hardened by the physiologic deposit of calcium salts. "By contrast, the mitochondrial-related genes MTND5P11 (log2FC −4.788), MTND4P12 (log2FC −3.897) and MTND4LP30 (log2FC −3.774) were downregulated in individuals with coronary calcifications." (PMID 40703140, 2025).